MMP1 (matrix metallopeptidase 1)
Diseases named in the same sentence as MMP1 in open-access papers (continued):
Sharing a sentence is not in itself a finding about the gene and the disease.
prostate carcinoma (53 papers, 2002 to 2025). A carcinoma that arises from epithelial cells of the prostate gland. "First, the quantity and sample size of included studies were relatively small even though we undertook a comprehensive literature search, especially for the association between MMP-1-1607 1G/2G polymorphism and risk of prostate cancer." (PMID 29249982, 2017). "Subgroup analysis based on ethnicity showed that MMP-1-1607 1G/2G polymorphism decreased the risk of prostate cancer among Caucasians under 2G vs. 1G model (OR = 0.54, 95% CI = 0.32–0.90) and 2G/2G vs. 1G/1G+1G/2G model (OR = 0.42, 95% CI = 0.19–0.91)." (PMID 29249982, 2017). "Many studies have examined the associations between MMP-2-1306 C/T (rs243865) and MMP-1-1607 1G/2G (rs1799750) polymorphisms and risk of prostate cancer." (PMID 29249982, 2017). "The most important advantage of our study is that this is the first study to examine the associationsofMMP-2-1306 C/T and MMP-1-1607 1G/2G polymorphisms with the risk of prostate cancer using meta-analysis." (PMID 29249982, 2017). "The aim of this meta-analysis was to shed some light on the genetic associations of MMP-2-1306 C/T and MMP-1-1607 1G/2G gene polymorphisms with prostate cancer susceptibility through incorporating all eligible studies." (PMID 29249982, 2017). "The present meta-analysis, for the first time, comprehensively evaluated the associations between MMP-2-1306 C/T and MMP-1-1607 1G/2G polymorphisms and risk of prostate cancer." (PMID 29249982, 2017). "Background and Objective: Studies suggests that matrix metalloproteinase (MMP)-2-1306 C/T and MMP-1-1607 1G/2G polymorphisms affect the risk of prostate cancer." (PMID 29249982, 2017). "Therefore, the results of association between MMP-1-1607 1G/2G polymorphism and risk of prostate cancer should be interpreted with caution." (PMID 29249982, 2017). "In summary, our findings suggest that the MMP-2-1306 C/T polymorphism is associated with elevated risk of prostate cancer, but MMP-1-1607 1G/2G polymorphism may have an inhibitory effect on the risk of prostate cancer in Caucasians." (PMID 29249982, 2017). "The decreased risk of prostate cancer concerning MMP-1-1607 1G/2G polymorphism in Caucasians might be spurious results or false positives." (PMID 29249982, 2017). "Therefore, we aimed to perform a meta-analysis to shed some light on the controversial conclusion pertaining to the associations of MMP-2-1306 C/T and MMP-1-1607 1G/2G polymorphisms with prostate cancer susceptibility." (PMID 29249982, 2017). "However, decreased risk of prostate cancer was observed in the Caucasians for MMP-1-1607 1G/2G polymorphism." (PMID 29249982, 2017). "Overall and subgroup analyses of MMP-1-1607 1G/2G polymorphism and prostate cancer susceptibility." (PMID 29249982, 2017). "MMP1 overexpression has been reported in prostate cancer, which we corroborated through IHC analyses." (PMID 37870957, 2023). "Intriguingly, MMP-1 had the ability to decrease AR signal and, concomitantly, enhance prostate cancer cell proliferation." (PMID 34966687, 2021). "In another study, prostate cancer cells cultured in 3D hydroxyapatite (HA)-collagen scaffolds exhibited reduced expression of MMP1 and MMP9 compared to 2D culture." (PMID 32967150, 2020). "Accordingly, a binary logistic regression analysis was performed to ascertain the contributions of both PSA and MMP-1 levels on the likelihood of participants having prostate cancer." (PMID 32425999, 2020). "Of note, multiple genes hitherto known to be associated with prostate cancer progression were observed in the top list of upregulated entities including but not limited to MYBL2, ESM1, PBK, and UBE2C in PC3, and MMP1, CCL5, and STC1 in DU145." (PMID 31493351, 2019). "Enforced PODXL expression in breast and prostate cancer cell lines promoted the migrated and invasive abilities by increasing expression of MMP-1 and MMP-9, and activating MAPK and PI3K signaling." (PMID 29748877, 2019).
prostate carcinoma (continued). "We also determined if polymorphisms in several Zn-dependent genes (MT2A, MMP-1, MMP-2, MMP-7, MMP-13) contributed to prostate cancer risk." (PMID 30036379, 2018). "MMP1 expression was significantly higher in prostate carcinoma versus in benign prostatic hypertrophy and in high- (Gleason scores 8, 9) and intermediate- (Gleason score 7) grade versus in low-grade (Gleason scores 4, 5, 6) prostate carcinomas." (PMID 30379883, 2018). "In this study we sought to analyze to what extent variations in serum Zn level and polymorphisms in MT2A, MMP-1, MMP-2, MMP-7 and MMP-13 are related to prostate cancer among Polish men." (PMID 30036379, 2018). "Further, overexpression of MMP1 in prostate cancer cells induced cells migration and invasion in vitro and the incidence of lung metastasis in vivo, but blocking MMP1 function significantly inhibited prostate cancer cell migration, invasion and metastasis." (PMID 30379883, 2018). "The elevated expression of matrix metalloproteinase 1 in ARCaPM (MMP1; P = 0.036, 1.61 log2 fold-change) is consistent with the functions attributed to this metalloprotease in prostate cancer progression and metastasis." (PMID 28424404, 2017). "In prostate cancer, MMP1 was down-regulated by FOXF2 whereas TIMP3, one of MMPs inhibitors, was up-regulated by FOXF2." (PMID 27487137, 2016). "We investigated the potential role of P4HA1-induced MMP1 in prostate cancer invasion in vitro using either specific siRNA or MMP1 inhibitor (FN-439)." (PMID 25115393, 2014). "EHF is a member of ETS homologus transcription factor and it was recently reported that re-expression of ESE3/EHF inhibited tumorigenic potential of prostate cancer, while MMP1 a cell surface metallopeptidase is a miR-221/222 and miR-1928 families target." (PMID 23479461, 2013). "RANK knockdown in PC-3 prostate cancer cells abrogated the effect of RANKL on MMP-1 gene expression." (PMID 23696795, 2013). "Previous work has demonstrated that MMP-1 levels in uncultured primary prostate carcinoma are very low and variable, whereas we have demonstrated that MMP-1 is strongly expressed in the bone metastases of prostate cancer patients." (PMID 11953862, 2002). "MMP1 expression was positively correlated with the aggressiveness of prostate cancer subsets." (PMID 36524848, 2023). "In addition, cDNA microarray analysis revealed an increased expression of PAR1 on bone-derived prostate cancer cell lines, confirming the role of bone microenvironment in promoting MMP-1/PAR1 pathway activation." (PMID 34966687, 2021). "In-vitro activation of the RANKL/RANK pathway promoted increased metastatic potential and MMP-1 expression of the prostate cancer PC3 cell line, with an interesting decreased presence of osteoclastogenesis and osteolytic lesions following MMP-1 knockdown in a mouse model of metastasis." (PMID 32585812, 2020). "It is suggested that MMP1 can become a future target for prostate cancer metastasis therapy and PC-3M-1E8 cell line may be a suitable model for testing MMP1-based therapeutics." (PMID 30379883, 2018). "The overall analyses of MMP-1-1607 1G/2G polymorphism and risk of prostate cancer showed no statistical significance." (PMID 29249982, 2017). "It has reported that MMP-9, rather than MMP-1 polymorphism variants were associated with pathological parameters in predicting the clinical outcome of prostate cancer patients." (PMID 28445160, 2017). "Similarly, RANK-expressing breast and prostate cancer cell lines demonstrate upregulation of matrix metalloproteinase-1 (MMP-1) and subsequent migration and invasion upon RANKL administration." (PMID 24432249, 2014). "MMP1 and 2 are known to be involved in prostate cancer progression, invasion and metastasis." (PMID 25115393, 2014). "With multiple MMP1 inhibitors in clinical trials, MMP1 could potentially serve as a surrogate target and benefit the prostate cancer patients that overexpress P4HA1." (PMID 25115393, 2014).
prostate carcinoma (continued). "Similarly, some authors found significantly higher expressions of MMP-1, -2 and -9 in prostate cancer tissues than in BPH tissues." (PMID 20160732, 2010). "In prostate cancer, P4HA1 could promote prostate cancer metastasis via regulating MMP1 expression." (PMID 34659558, 2021). "Here, we compare serum concentrations of metalloproteinase-1 (MMP-1) across individuals clinically diagnosed with prostate cancer (PCa) or benign prostatic hyperplasia (BPH), correcting results for the rs495366 single nucleotide polymorphism (SNP) that predisposes to differential MMP-1 levels." (PMID 32425999, 2020). "In prostate cancer cells, MMP-1 may be a critical, invasion promoting factor." (PMID 30197754, 2018). "Furthermore, we demonstrated miR-195 could inhibit prostate cancer cell motility by regulated the expression of c-Met, MMP1, MMP9." (PMID 26337460, 2015). "Furthermore Wnt5a induced the expression of metalloproteinase-1 (MMP-1) in prostate cancer." (PMID 23383207, 2013). "This included 2 matrix metallopeptidases, MMP1 and MMP14, both of which are overexpressed in human prostate tumors and promote invasion and metastasis of prostate cancer cells." (PMID 37870957, 2023). "In prostate cancer cells, for instance, TGF-β therapy leads to nuclear accumulation of MAPK1, which in turn promotes cancer cell EMT and upregulates the production of MMP1, MMP2/9, and MMP9." (PMID 37817112, 2023). "Mechanistic studies showed that Co-Sp reduced the expression of cyclin D1, cyclin E, CDK4, CDK2, MMP-9, MMP-1, and Bcl-2, and increased the expression of p21, cleaved caspase-9, cleaved caspase-3, cleaved PARP, and Bax in prostate cancer cells." (PMID 37313467, 2023). "As exhibited in 5C, the protein expressions of c-Met, MMP1, MMP9 were decreased in siRNA transfected prostate cancer cells." (PMID 26337460, 2015). "We next determined expression levels of MMP1 and FLRT3 in prostate tissue utilizing transcriptome sequencing data in prostate cancer." (PMID 25115393, 2014). "In this work we explore the role of MMP-1 in RANK+ breast and prostate cancer cells upon activation of RANKL-RANK pathway, and its ability to promote a metastatic behavior in these cells." (PMID 23696795, 2013). "HDAC1 could induce the activation of urokinase-type plasminogen activator (uPA), matrix metalloprotease-1 (MMP-1) and MMP-2, but suppressed E-cadherin in order to accelerate the invasion and migration of prostate cancer cells." (PMID 38800374, 2024). "In addition, functional analyses demonstrated that silencing MMP1 remarkably weakened the in vitro migratory and invasive capabilities of the PC-3M-1E8 cells, suggesting that MMP1 may be proved to be an ideal therapeutic target for overcoming prostate cancer metastasis." (PMID 30379883, 2018). "Another study on prostate cancer showed that Wnt5a bound to Fzd2 and Ror2 and activated JNK signaling, leading to expression of matrix metalloproteinase 1 (MMP1) through enhancing the recruitment of JunD to the AP-1 site of MMP1 promoter region, thereby inducing cell migration and invasion." (PMID 27571105, 2016). "MMP-1 has been used as a target of first-generation matrix metalloproteinase inhibitor, first as an adjunct to standard chemotherapy in non-small cell lung carcinoma patients and then in the treatment of HIV-related Kaposi's sarcoma and prostate cancers." (PMID 24278120, 2013). "To evaluate if RANKL-RANK pathway activation in RANK+ breast and prostate cancer cells could alter MMP-1 levels, we analyzed MMP-1 expression at both mRNA and protein levels upon RANKL stimulus." (PMID 23696795, 2013). "Indeed, by knocking down PHF19L, we observed significant induction of multiple genes known to promote changes in cytoskeleton and adhesion, extracellular matrix remodeling, invasion, and metastasis in prostate cancer (including SOX9, SOX4, MMP1, PLAU, EPCAM, CXCR4, LOX, and MET)." (PMID 32155117, 2020).
prostate carcinoma (continued). "The family of mammalian MMPs includes 24 members, but unlike MMP-1, -2 and -9, the role of MMP16 in prostate cancer has not been well investigated." (PMID 23593148, 2013).
pulmonary fibrosis (51 papers, 2008 to 2025). Chronic progressive interstitial lung disorder characterized by the replacement of the lung tissue by connective tissue, leading to progressive dyspnea, respiratory failure, or right heart failure. "Matrix metallopeptidase 1 (MMP-1) regulates extracellular matrix and collagen degradation, and its upregulation has been implicated in idiopathic pulmonary fibrosis and in CPFE." (PMID 39711778, 2024). "After adjustment for age, the PMN %, TNF-α, IL-1B, SDF-1α, MMP1, and calprotectin were associated with lung fibrosis (kurtosis and skewness) and density (HAA)." (PMID 34682263, 2021). "Wang and his colleagues reported that the frequency of MMP1 rs1799750 polymorphism was associated with lung fibrosis and lung destruction in TB patients." (PMID 26528997, 2015). "1G genotype of MMP1 rs1799750 polymorphism was reported to independently increase the risk for the development of moderate and advanced pulmonary fibrosis by 5- and 10-fold, respectively." (PMID 26528997, 2015). "MMP-1 polymorphism is associated with endobronchial TB that develops tracheobronchial stenosis, and with an increased risk for the development of lung fibrosis after TB infection." (PMID 23776649, 2013). "Bronchiectasis patients with the 1G genotype of MMP-1 polymorphism were more vulnerable to subsequent advanced lung fibrosis or destruction, as well as frequency of hospital admission due to disease exacerbation." (PMID 23776649, 2013). "Other data suggest that the polymorphism-related modifications of expression of the MMP-1 gene are also involved in the pathogenesis of idiopathic pulmonary fibrosis and liver cirrhosis in HCV-infected patients." (PMID 23108733, 2013). "This is the first report supporting this polymorphism of the promoter region of MMP-1 as linked to the severity of bronchiectasis, and as being an independent risk factor for increased tissue destruction and lung fibrosis in bronchiectasis." (PMID 23776649, 2013). "The links between the airways remodeling, lung fibrosis and MMP-1 polymorphisms have been recognized in several studies, including ours." (PMID 23776649, 2013). "Moreover, it was reported that patients with MMP-1 (-1607G) gene polymorphism are prone to develop lung fibrosis after pulmonary MTB infection." (PMID 26367274, 2015). "MMP-1 polymorphism may alter its transcriptional activity, and differentially modulate bronchial destruction and lung fibrosis." (PMID 23776649, 2013). "Bronchiectasis patients with MMP-1(-1607G) polymorphism may be more vulnerable to permanent lung fibrosis or airway destruction due to the enhanced MMP-1 and TGF-β1 activity." (PMID 23776649, 2013). "Patients with MMP-1(-1607G) polymorphism are more vulnerable to more extensive lung fibrosis 1 year after anti-tuberculosis treatment, which may be related to increased MMP-1 activity, leading to enhanced destruction of the matrix with subsequent fibrosis." (PMID 23776649, 2013). "Consequently, elevated inflammatory markers in LC are associated with increased expression of MMPs, including MMP-1, 2, 3, 7, 8, and 9, which have been linked to pathophysiological processes ranging from chronic fatigue symptoms to rapid progression of pulmonary fibrosis." (PMID 41463036, 2025). "The excessive increase of MMP-2 stimulates relatively more pulmonary fibrosis induced by PM2.5 than MMP-1." (PMID 37107342, 2023). "MMP1 gene is considered a biomarker gene of idiopathic pulmonary fibrosis (IPF), the appearance of MMP1 is strongly correlated with IPF in clinic studies." (PMID 36998092, 2023). "In normal processes, MMP1 breaks down the extracellular matrix and promotes the development of pulmonary fibrosis in IPF patients." (PMID 35480306, 2022). "A recent study showed that MMP1 expression can be induced by tobacco exposure and plays a major role in lung parenchyma destruction and pulmonary fibrosis." (PMID 35480306, 2022).
pulmonary fibrosis (continued). "We were particularly interested in the ECM associated genes and selected COL4A1, POSTN, MMP1 and MMP3 since they have been previously shown to be associated with pulmonary fibrosis." (PMID 33905434, 2021). "In support of these findings, E4 decreased FN, COL1α1, and PAI-1 levels in lung tissue cores from patients with pulmonary fibrosis, while increasing MMP-1 and uPA levels, demonstrating that E4 can reduce established and end-stage lung fibrosis." (PMID 34935642, 2021). "MMP-12: matrix metalloproteinase-1 (MMP-1) rs2276109*AA genotype has significant association in dcSSc, lcSSc, ATA positivity, and pulmonary fibrosis in an Italian SSc population." (PMID 26106387, 2015). "Previous studies have reported that DBT can reduce bleomycin-induced pulmonary fibrosis in rats by boosting matrix metalloproteinases, MMP-1, MMP-9, and TIMP-1 expression." (PMID 25861366, 2015). "Fukuda etal. demonstrated that increased MMP1 in epithelial cells in areas of intra-alveolar fibrosis in biopsy specimens from idiopathic pulmonary fibrosis patients." (PMID 26528997, 2015). "Despite its role as a degrading enzyme, MMP-1 levels have been paradoxically shown to be highly increased in human lung fibrosis, and variably reported to be increased, unchanged or decreased in SSc." (PMID 24289089, 2013). "Specifically, MMP-1, 8, and 9 are significantly elevated and correlate with disease severity, neutrophil degranulation, endothelial dysfunction, metabolic dysregulation, and pulmonary fibrosis." (PMID 41463036, 2025). "Inhibition of MMP1 with the small-molecule inhibitor GI254023X could significantly decrease lung fibrosis." (PMID 37221600, 2023). "It was found that MMP1 was higher in lung tissues of patients with idiopathic pulmonary fibrosis." (PMID 37221600, 2023). "Metalloproteinases are zinc-dependent endopeptidases that degrade all components of the ECM and possess antifibrotic activities in murine pulmonary fibrosis, especially matrix metalloproteinase-1 (MMP-1), which has the potential to limit fibrotic responses to injury." (PMID 35269381, 2022). "MMP1 can be activated by several pro-inflammatory cytokines and growth factors and its expression is increased in alveolar epithelial cells during pulmonary fibrosis, and it inhibits mitochondrial respiration and oxidative stress, while promoting cell proliferation and migration." (PMID 36120307, 2022). "Interestingly, genes related to vitamin D regulation (CYP27B1), inflammation (IRAK3) and pulmonary fibrosis (MMP1) were significantly induced by both viruses." (PMID 33301474, 2020). "Based upon clinical studies showing increasing concentration of MMP-1, -7, -8, and -9 in idiopathic pulmonary fibrosis (IPF) in blood and lung samples, targeting MMPs and their inhibitors may be new therapeutic approaches for IPF (reviewed in44)." (PMID 31980722, 2020). "Taken together, MMP-10 may be involved in the pathogenesis of pulmonary fibrosis, as with other MMPs, such as MMP-1 and -7." (PMID 26415518, 2015). "Both idiopathic pulmonary fibrosis and liver cirrhosis were associated with the 2G/2G MMP-1 variant, but unlike cancer the effect of this polymorphism is increased collagen content in the organs involved." (PMID 23108733, 2013). "We hypothesized that MMP-1 polymorphisms might lead to increased expression of MMP genes, and through increased activity of the enzymes, that would contribute to the lung fibrosis and/or airway destruction in patients with bronchiectasis." (PMID 23776649, 2013). "Up-regulation of MMP-1 gene and protein expression has been shown in human lung fibrosis." (PMID 23776649, 2013). "Similarly, MPs isolated from SSc patients with lung fibrosis showed a greater profibrotic profile, with an upward trend for Col1a1/MMP1 (median of 1.59 vs. 0.65, p=0.1) and Col1a2/MMP1 ratio (median of 2.42 vs. 0.91, p=0.07), but reduced ability to induce CCL2 (median of 0.89 vs. 1.51, p<0.05)." (PMID 33193304, 2020).